MUC6 (mucin 6, oligomeric mucus/gel-forming (gene/pseudogene))
Description:
May provide a mechanism for modulation of the composition of the protective mucus layer related to acid secretion or the presence of bacteria and noxious agents in the lumen. Plays an important role in the cytoprotection of epithelial surfaces and are used as tumor markers in a variety of cancers. May play a role in epithelial organogenesis.
Synonyms: MUC-6
Tractability: Antibody: its Gene Ontology location is reachable by antibodies, with high confidence; UniProt places it where antibodies can reach, with medium confidence; UniProt predicts a signal peptide or a membrane-spanning region.
Gene: Protein-coding gene on chromosome 11 (1,012,823 to 1,036,718, reverse strand). Ensembl gene ENSG00000184956.
Subcellular location: Secreted
Pathways (Reactome):
Disease: Defective C1GALT1C1 causes TNPS; Defective GALNT12 causes CRCS1; Defective GALNT3 causes HFTC
Metabolism of proteins: O-linked glycosylation of mucins; Termination of O-glycan biosynthesis
Immune System: Dectin-2 family
Gene Ontology:
Molecular function: extracellular matrix structural constituent
Biological process: maintenance of gastrointestinal epithelium
Cellular component: extracellular matrix; Golgi lumen; plasma membrane; extracellular region
Genetic constraint (gnomAD): Loss-of-function variants: 188 observed, 177.88 expected, observed/expected ratio (o/e) 1.06, 90% interval 0.94 to 1.19. The upper end of that interval is the gene's LOEUF score, 1.19, which puts it in group 5 of 6, group 1 being the genes least tolerant of losing a copy. Missense variants: 2,704 observed, 2,812.8 expected, observed/expected ratio (o/e) 0.96, 90% interval 0.93 to 0.99. Synonymous variants: 1,227 observed, 1,187.8 expected, observed/expected ratio (o/e) 1.03, 90% interval 0.99 to 1.08.
Homologues: Orthologues: chimpanzee MUC6 (85% identical), mouse Muc6 (59% identical), pig MUC6 (56% identical), dog MUC6 (52% identical), rat Muc6 (40% identical), tropical clawed frog muc6 (38% identical). Paralogues in human: MUC5AC (29% identical), MUC5B (29% identical), MUC19 (23% identical), MUC2 (20% identical), OTOG (18% identical), VWF (17% identical), OTOGL (15% identical), FCGBP (14% identical), TECTA (13% identical), ZAN (10% identical), KCP (9% identical), CRIM1 (8% identical), and 7 more.
Diseases named in the same sentence as MUC6 in open-access papers:
MUC6 is named in the same sentence as 160 diseases in open-access papers, as found by Europe PMC text mining. Sharing a sentence is not in itself a finding about the gene and the disease. The quoted sentences say what the papers report.
gastric cancer (40 papers, 2004 to 2025). A primary or metastatic malignant neoplasm involving the stomach. "Muc6 is specifically expressed in gastric mucous neck cells and deep glands, and its loss or altered expression is frequently observed in human gastric cancer and precancerous lesions." (PMID 40673273, 2025). "For instance, muc6-deficient (Muc6−/−) mice were generated to observe gastric cancer progression." (PMID 40673273, 2025). "MUC6, as a previously identified gastric cancer driver gene, has a high mutation rate (20%) in GLP." (PMID 36450891, 2023). "Research has revealed that the methylation of the MUC6 promoter may cause a considerable decrease in MUC6 expression in gastric cancer and drive its progression." (PMID 37581476, 2023). "MUC6 mutation in gastric cancer is associated with a poor prognosis." (PMID 35453635, 2022). "The downregulation of MUC6 may contribute to malignant transformation of gastric epithelial cells and underlie the growth, invasion, metastasis, and differentiation of gastric carcinoma." (PMID 35453635, 2022). "On the other hand, the abnormal expression of the MUC6 gene, usually associated with increased tumor cell mobility, has been found in many malignant tumors, such as gastric cancer, duodenal cancer, breast cancer, pancreatic cancer, endometrial cancer, CRC, and lung cancer." (PMID 32695780, 2020). "The susceptibility to gastric cancer may be related to variation in MUC6 gene expression." (PMID 34996478, 2022). "The 100% penetrance of gastric cancer in this model demonstrates the critical protective role of Muc6 in maintaining gastric epithelial integrity, reflecting clinical observations where Muc6 loss is associated with increased cancer risk in humans." (PMID 40673273, 2025). "Reduced expression of MUC5AC and MUC6 has been reported as a potential predictor of poor prognosis in gastric cancer.17,18) Consistent with these evidence, the present case showed high malignant potential, with multiple recurrences." (PMID 40589560, 2025). "The expression of MUC6 in gastric carcinomas, compared with that in adenomas and normal mucosa, was relatively in low level." (PMID 39886661, 2024). "MUC5AC stains positive in normal gastric foveolar epithelium and gastric cancers, and MUC6 shows positive staining in normal pyloric glands of the stomach and also gastric cancers." (PMID 36001283, 2023). "Other authors had addressed the prognostic role of MUC6 expression in 225 gastric cancers, 101 pancreatic cancers, 85–100 cholangiocarcinomas, 73 salivary gland carcinomas, and 36 ovarian cancers." (PMID 37057870, 2023). "The mucin expression profile of GOJc was mixed, containing high MUC2 gene expression consistent with oesophageal and high MUC6 gene expression consistent with gastric cancers." (PMID 37958425, 2023). "MUC2 expression decreases during metaplasia from normal gastric mucosa to intestinal-type, whereas MUC5AC is upregulated with more aggressive gastric tumours, and MUC6 is downregulated in gastric cancer." (PMID 37958425, 2023). "For example, the MUC6 gene is one of the mucin genes that make up the gastric mucosa, and its expression is downregulated in precancerous lesions and gastric cancer tissues." (PMID 35865460, 2022). "AIG-related gastric cancer patients had higher levels of MUC6 and MUC5AC expression in the gastric glands." (PMID 35453635, 2022). "The tumor-suppressive effect of MUC6 in WT is generally consistent with its roles in gastric cancer, colorectal cancer, intestinal ovarian mucinous neoplasms and pancreatic cancer." (PMID 35574418, 2022).
gastric cancer (continued). "This article reviews the diagnostic and prognostic values of molecular markers in complete (MUC2) and incomplete (MUC2, MUC5AC, and MUC6) intestinal metaplasia, gastric dysplasia/intra-epithelial neoplasia, and early gastric cancer." (PMID 34206291, 2021). "In a case-control study of gastric cancer, five minisatellites (MS1-MS5) were identified in the genomic structure of MUC6, and MUC6-MS5 alleles from cancer-free controls and individuals with gastric cancers were scored." (PMID 32695780, 2020). "The decreased expression of MUC5AC and MUC6 mucin in gastric carcinomas were confirmed in the present study." (PMID 16545139, 2006). "It has been reported that methylation of the MUC6 promoter may lead to significant downregulation of MUC6 in gastric cancer and promote the progression of gastric cancer." (PMID 36118520, 2022). "So far, most studies on polymorphisms in MUC6 have been dedicated to gastric cancer, without any significant associations." (PMID 31091244, 2019). "It remains to be investigated whether all mucins (MUC1, MUC2, MUC4, MUC 5AC, MUC 5B, MUC6 etc.) may carry these sialylated and sulfated oligosaccharidic sidechains detected in intestinal metaplasia, gastric carcinoma and cholelithiasis." (PMID 17565665, 2007). "The gastric cancer markers CK7 (-), TTF-1 (-), and NapsinA (-) completely exclude lung derived metastasis, while Muc-2 (+), Muc-5AC (+), and Muc-6 (+) are gastric mucinous phenotypes, indicating gastric primordia." (PMID 40837582, 2025). "The expression of MUC5AC, MUC6, MUC2, and CD10 was shown in 346 (52.7%), 425 (64.7%), 149 (22.7%), and 176 (26.8%) of the 657 early differentiated gastric cancer lesions, respectively." (PMID 36977979, 2023). "In the resected gastric cancer tissues, mucin expression rates were 71.4% for MUC1, 78.6% for MUC2, 75.4% for MUC5AC, and 33.3% for MUC6." (PMID 36831343, 2023). "Gastric cancers with a pure AIG background had higher proportions of MUC5AC positivity (8/8 vs. 2/8, p = 0.0007) and MUC6 positivity (8/8 vs. 2/8, p = 0.0007) than did cancers with H. pylori infection." (PMID 35453635, 2022). "Immunohistochemical staining in the matched cohort showed that AIG-related gastric cancer had higher MUC5AC expression (p = 0.0007) and MUC6 expression (p = 0.0007)." (PMID 35453635, 2022). "Immunohistochemistry revealed that MUC5AC and MUC6 were negative in primary gastric cancer, lymph node metastases, and gallbladder lesions." (PMID 40589560, 2025). "Mucin 6 (MUC6) immunostaining and tumor phenotype in breast cancers of no special type, colon adenocarcinomas, endometrioid endometrium carcinoma, serous ovarian cancers, pancreatic adenocarcinomas, and gastric cancers." (PMID 37057870, 2023). "For example, a lower expression of genes that may play an important role in suppressing gastric cancer (GKN1, LIPF, ANXA10, MUC6, PSCA, and SNHG5) was found." (PMID 35625760, 2022). "Our present findings show that the gastric and intestinal phenotypic marker expression of the tumour, determined by immunohistochemical staining for HGM, MUC6, MUC2 and CD10, can be used to predict the pattern of gastric carcinoma recurrence after curative resection." (PMID 15354218, 2004). "Several authors have reported that gastric carcinomas can be classified as having either a gastric (G), gastric and intestinal mixed (GI) or intestinal (I) phenotype, depending on the immunopositivity of human gastric mucin (HGM), MUC6, MUC2 and CD10 stainings." (PMID 15354218, 2004). "In conclusion, our present findings show that the gastric and intestinal phenotypic marker expression of the tumour, determined by the HGM, MUC6, MUC2 and CD10 expression patterns, may be used to predict the recurrence pattern of gastric carcinomas after curative resections." (PMID 15354218, 2004). "Most of the other colorectal and gastric cancer markers such as CDX2, MUC1, MUC2, and MUC6 were also negative." (PMID 34397857, 2021).
gastric cancer (continued). "The gastric carcinoma markers MUC2, MUC5AC, and MUC6 were expressed weakly or not at all." (PMID 31367188, 2019).
colorectal cancer (14 papers, 2014 to 2026). A primary or metastatic malignant neoplasm that affects the colon or rectum. "We identified a significant association between MUC6 expression and MMRd, a relationship previously reported in colorectal carcinoma." (PMID 39755998, 2025). "That MUC6 expression was tightly linked to microsatellite instability (MSI) in colorectal carcinoma in our study is consistent with two recent studies on traditional and sessile serrated adenomas." (PMID 37057870, 2023). "While MUC2 has been suggested to be specific for the GI tract and mainly expressed in colorectal cancer, especially mucinous colorectal AC, MUC6 has been reported to be positive more often in upper GI tract and pancreatic AC." (PMID 37349623, 2024). "MUC6 is a gastric mucin that is ectopically expressed in colorectal cancer." (PMID 36982838, 2023). "MUC6 expression has been suggested to inhibit tumor invasion in pancreatic cancer, which may apply to colorectal cancer as well and could play a role in the favourable prognosis known to characterize Lynch syndrome tumors." (PMID 28824332, 2017). "In summary, we identified significant differences in the immunoprofiles of colorectal cancers linked to FCCTX and Lynch syndrome with a more sporadic-like profile in the former group and a more distinct profile with frequent MUC6 positivity in the latter group." (PMID 28824332, 2017). "A heatmap of the top 50 differentially expressed genes was generated, highlighting that genes such as SPRR family members, MUC6, KRT family genes, SLC26A9, MMP7, PRSS56, and SFRP1 were highly expressed in the colorectal cancer group." (PMID 41595533, 2026). "In our study, TCGA analysis revealed that genes such as those from the SPRR family, MUC6, KRT family, SLC26A9, MMP7, PRSS56, and SFRP1 were highly expressed in the colorectal cancer group." (PMID 41595533, 2026). "The MUC profile in the FCCTX subset was more akin to that of unselected colorectal cancers with MUC2 expression reported in 40–54%, MUC5AC in 6–10% and MUC6 in 4%." (PMID 28824332, 2017). "In appendiceal carcinoma, MUC3, MUC6 and MUC16 had lower expression, MUC2 expression was markedly higher, and MUC1 expression was higher than the respective rates in colorectal carcinoma." (PMID 25551773, 2014). "In colorectal carcinoma, these rates are MUC1, 24–32%; MUC2, 38%; MUC3, 74%; MUC4, 94%; MUC5AC, 34–50%; MUC6, 39%; and MUC16, 64%." (PMID 25551773, 2014). "We investigated the core protein-expression levels of MUC2, MUC5AC, MUC6, and CD10 because altered expressions of these proteins may be significantly correlated with the biological behavior of colorectal carcinoma and, possibly its prognosis." (PMID 30458818, 2018). "Indeed, a recent report on the clinical significance of secreted gel-forming MUCs in colorectal carcinomas demonstrated a favorable influence on the outcome in case of gain in aberrant MUC expression, particularly of MUC6 expression." (PMID 28824332, 2017). "In the study, we used the same immunohistochemical antibody and cutoff criteria and demonstrated that CLDN18 expression was seen in 27% of colitis-associated colorectal carcinomas with an association of MUC5AC expression, while without significant association with MUC6 status." (PMID 39164422, 2025). "Whereas MUC5, MUC6, MUC16, and MUC20 are absent from the normal colon and are expressed in colorectal cancers." (PMID 36900282, 2023).
adenoma (13 papers, 2010 to 2025). A neoplasm arising from the epithelium. "Since APC and KRAS are the most frequently mutated driver genes in the adenoma-to-carcinoma sequence, they could be expected to demonstrate alterations more frequently; moreover, the MUC6 and MUC3A mutations were the most frequent, followed by KRAS mutations, principally in TAs and VAs/TVAs." (PMID 40002249, 2025). "Numerous groups have reported varying percentages for MUC6 expression amongst different subtypes of colonic polyps, with values ranging from 0–16.9% for hyperplastic polyps, 0–16% for adenomas, and 20–100% for sessile serrated adenomas (SSA)." (PMID 36900282, 2023). "To clarify what types of adenomas are associated with GDM, we performed IHC for CDX-2 (a marker of intestinal origin), MUC5AC (a marker of gastric foveolar mucin), and MUC6 (a marker of gastric pyloric gland mucin)." (PMID 28467793, 2017). "Importantly, mucins in Smad4Δ/Δ adenomas were among the DEGs with Muc4, Muc20, Muc2 being upregulated and Muc6 being downregulated (padj p < 0.05)." (PMID 40348815, 2025). "Therefore, the relationship between MUC6 and sessile serrated adenoma is controversial." (PMID 32695780, 2020). "Specifically, they were identified as PGAs, adenocarcinomas consisting of diffuse MUC6-positive atypical cells, and NOS-type adenomas." (PMID 40463821, 2025). "The adenoma tissue was diffusely positive for MUC5AC, while MUC6 was focally positive, indicating that the epithelium that composed the adenoma was a gastric foveolar phenotype." (PMID 35508985, 2022). "Two foveolar-type adenomas showed CDX-2(-), MUC5AC(+), MUC6(-), and 2 pyloric gland adenomas showed CDX-2(-), MUC5AC(-), MUC6(+)." (PMID 28467793, 2017). "The other 21 adenomasshowed nuclear β-catenin expression and these were all intestinal-type adenomas identified with expressions of CDX2(+), MUC5AC(-), and MUC6(-)." (PMID 28467793, 2017). "Immunohistochemical analysis of SSC adenomas of the pancreas develops positivity for Cam 5.2, CK7, PAS, epithelial membrane antigen (EMA), NSE, alpha-inhibin, MUC6, and calponin." (PMID 27525151, 2016). "While these two mucins were reported previously to be more expressed in medium size/stage adenomas, more recent data reports MUC5AC to be involved in early stages of malignant transformation, and MUC6 in final stages." (PMID 20929551, 2010). "While the glands at the base of the adenoma showed diffuse staining of MUC6 but no gastrin staining, composed of columnar epithelium with only a small number of main cells scattered, indicating that it was a pseudopyloric gland metaplasia." (PMID 35508985, 2022). "MUC5AC and MUC6 were also found in a high proportion of villous and tubulovillous adenomas but not in normal colonic biopsies." (PMID 26500890, 2015). "MUC1 and MUC6 were absent in all hyperplastic polyps and their expression was higher in serrated and traditional adenomas." (PMID 20929551, 2010).
gastric adenocarcinoma (10 papers, 2019 to 2023). "Interestingly, patients with stomach adenocarcinoma and mutated MUC6 had better overall survival prognose, as compared to patients with wild-type MUC6." (PMID 37504272, 2023). "We also evaluated αGlcNAc expression in human gastric adenocarcinoma and pyloric gland adenoma, which precedes gastric adenocarcinoma, and observed frequent loss of αGlcNAc expression in MUC6-positive differentiated-type adenocarcinoma and high-grade pyloric gland adenoma." (PMID 31506488, 2019). "MUC6 immunostaining was most frequent in mucinous carcinomas of the breast (44%), adenocarcinomas of the stomach (30%–40%) and esophagus (35%), and neuroendocrine carcinomas of the colon." (PMID 37057870, 2023). "The highest prevalences of MUC6 expression were seen in carcinomas of the breast, adenocarcinomas of the stomach, esophagus, colorectum, and the pancreas, as well as in carcinomas of the endometrium and the ovary." (PMID 37057870, 2023). "Immunohistochemical staining of CD10, MUC2, MUC5AC, and MUC6 was performed in 257 tissue samples from patients with early differentiated gastric adenocarcinomas." (PMID 34256780, 2021). "MUC6 expression was unrelated to clinico‐pathological features in serous ovarian carcinomas, endometrioid endometrial carcinomas, ductal adenocarcinomas of the pancreas, and in gastric adenocarcinomas." (PMID 37057870, 2023). "Therefore, immunohistochemical findings for pepsinogen-I and MUC6 are useful for the differential diagnosis of gastric adenocarcinoma of the fundic gland type (chief cell predominant type), especially when CGA is also positive." (PMID 33097069, 2020). "Immunohistochemistry revealed that the tumor cells were positive for MUC5AC, but negative for MUC2 and MUC6, leading to a final diagnosis of foveolar-type gastric adenocarcinoma." (PMID 37663228, 2023). "MUC5AC and MUC6 expression decreases during esophageal adenocarcinoma formation, but not gastric adenocarcinoma progression." (PMID 36994101, 2023).